CNTNAP4 (contactin associated protein family member 4)
Diseases named in the same sentence as CNTNAP4 in open-access papers:
CNTNAP4 is named in the same sentence as 40 diseases in open-access papers, as found by Europe PMC text mining. Sharing a sentence is not in itself a finding about the gene and the disease. The quoted sentences say what the papers report.
autism (11 papers, 2010 to 2024). Persistent deficits in social interaction and communication and interaction as well as a markedly restricted repertoire of activity and interest as well as repetitive patterns of behavior. "Impaired Cntnap4 function is implicated in neurological disorders, such as autism; however, the role of Cntnap4 on memory processing is poorly understood." (PMID 37933376, 2023). "We also identified PSGs associated with communication disorders, such as autism (CNTNAP4, AHI1, FAN1, SNTG2, and GRIP1) and dyslexia (KIAA0319)." (PMID 33441416, 2021). "Cntnap4, a risk gene of autism, has been implicated to participate in PD pathogenesis." (PMID 37087484, 2023). "Loss of CNTNAP4 in interneurons has been linked to autism, schizophrenia, and epilepsy." (PMID 32194851, 2020). "Studies have demonstrated a potential association of CNTNAP4 autism or alcohol dependence." (PMID 27682028, 2016). "We utilized the Cntnap4−/− mice previously generated by our lab36 to detect its mechanism in promoting autism-like behaviours." (PMID 36395738, 2022). "Importantly, in addition to the association with cognitive impairment, LOAD, and PD (this study), CNTNAP4 polymorphisms have been shown to be associated with some other phenotypes such as serum level of cholesterol and sphingolipids, glaucoma, autism, and D-amphetamine response." (PMID 24223195, 2013). "The cell adhesion molecules NRXN1 and CNTNAP4 are involved in mirror neuron activity and empathic behavior, and RELN has been reported to functionally interact with oxytocin and both neuropeptides have been implicated in autism pathophysiology." (PMID 32966280, 2020). "Increasing evidence supports the fact that CNTNAP4 may be related to autism, childhood-onset schizophrenia, and epilepsy, highlighting the possible important role that CNTNAP4 may have in neurological development 14-17." (PMID 32194851, 2020). "However, other top DEGs including CNTNAP4, SLC1A2, and GABRG3 have also been shown to underly irregular firing patterns in the context of epilepsy or autism and could be contributing to the disease mechanism." (PMID 38280846, 2024). "Furthermore, the PSGs expressed in the brain and under the highest positive selection include CNTNAP4, FAN1, SNTG2, and KIAA0319, which also display high levels of expression in the cerebellum and have been associated with communication disorders, such as autism and dyslexia." (PMID 33441416, 2021). "Absence of Cntnap4 has been observed to induce autism-related behavioural abnormality such as over-grooming by disturbing GABAergic signalling." (PMID 36395738, 2022).
epilepsy (5 papers, 2020 to 2025). A brain disorder characterized by episodes of abnormally increased neuronal discharge resulting in transient episodes of sensory or motor neurological dysfunction, or psychic dysfunction. "Specifically, CNTNAP4 is decreased in the brains of both epileptic patients and mice: Knock-down of CNTNAP4 in mice increased epilepsy susceptibility, while its overexpression decreased epileptic behavior." (PMID 36482407, 2022).
Alzheimer disease (3 papers, 2013 to 2025). A progressive, neurodegenerative disease characterized by loss of function and death of nerve cells in several areas of the brain leading to loss of cognitive function such as memory and language. "Prevalence of the CNTNAP4 CNVR6782.1del/del variant in late-onset Alzheimer’s disease." (PMID 24223195, 2013).
breast carcinoma (3 papers, 2013 to 2024). "Meanwhile, in breast cancer patients, 16q deletion is associated with survival, molecular subtypes, mRNA expression, and germline haplotypes, and the cell recognition gene CNTNAP4 is included." (PMID 32596394, 2020). "In some tumors (breast cancer, adrenocortical adenoma), one of the most frequently deleted regions locates to the 16q23.1 region and overlaps the CNTNAP4 locus." (PMID 24223195, 2013). "CNTNAP4 may serve as a prognostic biomarker for hepatocellular carcinoma, prostate cancer, and breast cancer." (PMID 38584840, 2024).
Parkinson disease (3 papers, 2013 to 2022). A progressive degenerative disorder of the central nervous system characterized by loss of dopamine producing neurons in the substantia nigra and the presence of Lewy bodies in the substantia nigra and locus coeruleus. "Prevalence of the CNTNAP4 CNVR6782.1del/del variant in Parkinson’s disease." (PMID 24223195, 2013). "CNTNAP4 is also highly enriched in dopaminergic (DA) neurons in the substantia nigra (SN), however, few studies have investigated the role of CNTNAP4 in DA neurons, and whether CNTNAP4 deficiency in DA neurons contributes to Parkinson's disease (PD) remains unclear." (PMID 32194851, 2020). "In conclusion, we have demonstrated associations of the CNTNAP4 gene and its CNVR6782.1del/del polymorphic variant with longevity, healthy aging, and aging-related pathologies such as cognitive impairment and, tentatively, Alzheimer’s and Parkinson’s diseases." (PMID 24223195, 2013).
Cognitive impairment (2 papers, 2013 to 2023). Abnormal cognition is characterized by deficits in thinking, reasoning, or remembering. "In this study, we describe the dysfunction of GABAergic transmission as a link between microglia activation and cognitive impairment caused by Cntnap4 deficiency." (PMID 37933376, 2023). "Hippocampal Cntnap4 deficiency was associated with cognitive impairment via inducing pro‐inflammatory response in females." (PMID 37933376, 2023). "To reveal the role of microglia in cognitive impairment due to Cntnap4 deficiency, we established a biomimetic microglial delivery strategy." (PMID 37933376, 2023). "Indeed, in this study, the association of the CNTNAP4 CNVR6782.1del/del variant with cognitive impairment, defined as an MMSE score of <24, was found for community-dwelling females ≥80 years old." (PMID 24223195, 2013). "We report that hippocampal Cntnap4 deficiency in female mice, including mice injected with adeno‐associated virus (AAV)‐packaged Cntnap4 shRNA and heterozygous Cntnap4 knockout (Cntnap4+/−) mice, manifests as cognitive impairment and dysfunctional synaptic transmission." (PMID 37933376, 2023). "Thus, increased GABA in microglia of Cntnap4+/− mice may be insufficient to suppress the pro‐inflammatory response and cognitive impairment." (PMID 37933376, 2023). "Prevalence of the CNTNAP4 CNVR6782.1del/del variant in ≥80 years old seniors (PolSenior collection) with cognitive impairment, and with other pathologies in the absence of cognitive impairment." (PMID 24223195, 2013).
depression (2 papers, 2020 to 2022). "The downregulation of CNTNAP4 has been demonstrated in several neurological conditions, including temporal lobe epilepsy and major depressive disorder." (PMID 36482407, 2022). "We observed a weak correlation between NXPH1 (r = 0.52, p = 0.013), CNTNAP4 (r = 0.42, p = 0.049) and MADRS in 22 depression patients from whom this assessment scale was available." (PMID 32398672, 2020).
cognitive decline (1 paper, 2023). "To explore the mechanisms underlying hippocampal Cntnap4 knockdown‐induced cognitive decline, we performed RNA‐seq." (PMID 37933376, 2023). "Because cognitive decline is found in females and downregulated DEGs were linked with sterol metabolic and biosynthesis process, we next examined differential metabolites between Ctrl shRNA and Cntnap4 shRNA by metabolomic analysis." (PMID 37933376, 2023). "Taken together, our results suggest that Cntnap4 loss is a cause of cognitive decline that is associated with inflammatory response, for which microglial supplementation of PLX3397 may serve as an intervention." (PMID 37933376, 2023). "Furthermore, MNPs@PLX attenuated Cntnap4 loss‐induced cognitive decline, dysfunctional synaptic plasticity, and pro‐inflammatory response." (PMID 37933376, 2023). "Together, our findings show loss of Cntnap4 causes pro‐inflammatory cognitive decline that is effectively prevented by supplementation with microglia‐specific inhibitors; thus validating the targeting of microglial function as a therapeutic intervention in neurocognitive disorders." (PMID 37933376, 2023). "Taken together, these data indicate that MNPs@PLX attenuates cognitive decline, dysfunctional synaptic plasticity, and microglia activation in female Cntnap4+/− mice." (PMID 37933376, 2023). "A biomimetic microglial nanoparticle system (MNPs@PLX) was established for precise microglial delivery of FDA‐approved PLX3397 to attenuate cognitive decline, dysfunctional synaptic plasticity, and pro‐inflammatory response in female heterozygous Cntnap4 knockout mice." (PMID 37933376, 2023). "The underlying mechanisms may involve pro‐inflammatory response resulting from impaired GABAergic transmission, given that GABA supplementation rescues the cognitive decline and dysfunctional synaptic transmission in female Cntnap4+/− mice." (PMID 37933376, 2023). "Furthermore, MNPs@PLX attenuates cognitive decline, dysfunctional synaptic plasticity, and pro‐inflammatory response in female heterozygous Cntnap4 knockout mice." (PMID 37933376, 2023).
osteosarcoma (1 paper, 2023). A usually aggressive malignant bone-forming mesenchymal neoplasm, predominantly affecting adolescents and young adults. "First, expression of Cntnap4 was verified in different sets of human osteosarcoma tissues and primary cells." (PMID 36599925, 2023). "Cntnap4 exerts its effects partly via interaction with NELL-1, an osteosarcoma associated protein, and subsequent positive regulation of MAPK intracellular components." (PMID 36599925, 2023). "We conclude that NELL1/CNTNAP4 activates ERK/MAPK signaling, and this is a feature of an aggressive phenotype in osteosarcoma." (PMID 36599925, 2023). "Significantly, several genetic alterations that collectively interact with CNTNAP4 have poor prognosis in patients with soft tissue sarcoma, although no data for osteosarcoma is yet known." (PMID 36599925, 2023).
sarcoma (1 paper, 2023). A usually aggressive malignant neoplasm of the soft tissue or bone. "Here, CRISPR/Cas9 gene deletion of CNTNAP4 reduced OS tumor growth, sarcoma-associated angiogenesis, and pulmonary metastases." (PMID 36599925, 2023). "In summary, we report that CNTNAP4 gene deletion mitigates aggressive sarcoma behavior in an orthotopic model of human OS, characterized by delayed tumor onset, decreased tumor progression, reduced tumor-associated angiogenesis and diminished ERK/MAPK signaling." (PMID 36599925, 2023). "Thus far, significant similarities had been observed between CNTNAP4 KO sarcoma cells and those effects we recently reported in NELL1 KO cells." (PMID 36599925, 2023). "Finally, human primary cells and tissues in combination with sequencing datasets confirmed the significance of CNTNAP4 signaling in human sarcomas." (PMID 36599925, 2023). "This molecular data has shown that NELL-1 is a high-affinity ligand for CNTNAP4 and implies that autocrine NELL-1/CNTNAP4 signaling within sarcoma cells could be a biologically relevant axis that regulates OS disease progression." (PMID 36599925, 2023). "Therefore, future studies investigating the role of NELL-1/CNTNAP4 function in sarcoma progression will likely require prospective data collection on single tumor types, including bone-associated sarcomas." (PMID 36599925, 2023). "Second, it is clear, as alluded to, that both NELL-1 and CNTNAP4 have several binding partners that may play partially redundant roles in sarcoma disease progression." (PMID 36599925, 2023). "CNTNAP4 knockout (KO) in OS tumor cells largely phenocopied the effects of NELL-1 KO, including reductions in sarcoma cell attachment, migration, and invasion." (PMID 36599925, 2023). "In summary, our findings demonstrate the biological importance of NELL-1/CNTNAP4 signaling axis in disease progression of human sarcomas and suggest that targeting the NELL-1/CNTNAP4 signaling pathway represents a strategy with potential therapeutic benefit in sarcoma patients." (PMID 36599925, 2023). "This suggests that NELL-1 exerts at least some effects independent of Cntnap4 and that NELL-1 could have more diverse effects outside of Cntnap4-MAPK-FAK signaling in sarcoma biology." (PMID 36599925, 2023).
α-synucleinopathy (1 paper, 2023). "Taken together, we provide evidence that Cntnap4 partial deficiency accelerates α-synuclein pathology, nigrostriatal neuron degeneration, and motor disorders in α-synucleinopathy mouse models of PD." (PMID 37087484, 2023).
cancer (3 papers, 2017 to 2023). A tumor composed of atypical neoplastic, often pleomorphic cells that invade other tissues. "Consistent with this notion, we identified a subset of this signature containing DPP4, BCAT1, CNTNAP4 and CDH3, whose expression are either the same or increased in CRPC compared to primary PC, and whose gene alterations correlate with a more rapid onset of cancer." (PMID 28055971, 2017).
neurodegenerative disease (3 papers, 2020 to 2024). A disorder of the central nervous system characterized by gradual and progressive loss of neural tissue and neurologic function. "There is a known relationship between CNTNAP4 and neurodegenerative diseases, and a CNV variant in this gene was found to be inversely associated with healthy aging." (PMID 38844476, 2024). "We previously demonstrated that Cntnap4 deficiency contributes to the pathogenesis of neurodegenerative diseases." (PMID 36395738, 2022). "Although it has been suggested that the CNTNAP4 gene and its intronic copy number variation (CNV) polymorphism are associated with aging and aging-related disease, such as PD and AD in females 19, the role of CNTNAP4 in neurodegenerative disease remains unclear." (PMID 32194851, 2020).
neurological disorders (3 papers, 2013 to 2023). "Taking into account the predominant localization of CASPR4 in various brain structures and its similarity to CASPR2, we hypothesized that the CNTNAP4 variants are also associated with nervous system disorders." (PMID 24223195, 2013).
tumor (3 papers, 2016 to 2023). "Together, our data demonstrate that CNTNAP4 gene deletion slows OS tumor growth and reduces metastatic spread in an orthotopic xenograft model." (PMID 36599925, 2023). "Transcriptomic analysis combined with protein phospho-array demonstrated notable reductions in the MAPK/ERK signaling cascade with CNTNAP4 deletion, and the ERK1/2 agonist isoproterenol restored cell functions among CNTNAP4 KO tumor cells." (PMID 36599925, 2023). "A clear reduction of tumor size was observed in CNTNAP4 KO group when compared to the control group (49.1% reduction at 28 days post-implantation)." (PMID 36599925, 2023). "Tumor-associated angiogenesis also showed a significant reduction among CNTNAP4 KO implants compared to control (81.5% reduction in CD31 labeling), in line with prior reports of the angiogenic effects of CNTNAP4 signaling." (PMID 36599925, 2023). "We have now extended this work to elucidate the role of CNTNAP4, a high-affinity receptor for NELL-1 in mediating tumor progression." (PMID 36599925, 2023). "Similarly, MAPK and FAK signaling pathways were significantly downregulated in CNTNAP4 KO cell clones, but to a lesser extent in NELL1 KO tumor cells." (PMID 36599925, 2023).
movement disorder (2 papers, 2020 to 2023). Neurological conditions resulting in abnormal voluntary or involuntary movement, which may impact the speed, fluency, quality and ease of movement. "Previously, we reported that loss of function of contactin-associated protein-like 4 (Cntnap4) induces parkinsonian phenotypes, such as dopaminergic (DA) neuronal death and movement disorders, by regulating mitophagy." (PMID 37087484, 2023). "Notably, elimination of microglia attenuated the movement disorder in the Cntnap4+/− + AAV-hα-Syn mice in the OFT and grasping test, improved nigrostriatal DA neuronal death, and slightly decreased the endogenous α-synuclein level." (PMID 37087484, 2023). "The behavioral results suggested that CNTNAP4 knockout mice showed movement disorder." (PMID 32194851, 2020).
psychiatric disorder (2 papers, 2020 to 2025). A disorder characterized by behavioral and/or psychological abnormalities, often accompanied by physical symptoms. "It reveals a biosignature of decreased synaptic protein levels including NRXN3 and CNTNAP4 in the CSF of psychiatric disorders, mainly MDD." (PMID 32398672, 2020). "Our study presents the first report on significantly decreased levels of NRXN3 and CNTNAP4 in the CSF of major psychiatric disorders, mainly MDD." (PMID 32398672, 2020).
brain diseases (1 paper, 2021). "Almost half of them were involved in axon-related processes (RTN4R, CNTNAP4, ADAM22, PCSK1N, NRXN1), which could indicate that the neurodegenerative mechanisms may be different between these brain diseases." (PMID 33603109, 2021).
neurodevelopmental disorder (1 paper, 2023). A behavioral and cognitive disorder with onset during the developmental period that involves impaired or aberrant development of intellectual, motor, or social functions. "It would also be of great interest to conduct similar studies for other members of the Contactin Associated Protein family, which have also been associated with neurodevelopmental disorders such as ASD, especially Caspr3/CNTNAP3, Caspr4/CNTNAP4, and Caspr5/CNTNAP5." (PMID 36793543, 2023).
CNTNAP4 also shares sentences with these, for which no sentence is quoted: Intellectual disability (3 papers); schizophrenia (3); autism spectrum disorder (2); adrenocortical adenoma (1); alcohol dependence (1); aneurysm (1); Angelman syndrome (1); childhood-onset schizophrenia (1); chronic pancreatitis (1); communication disorder (1); dyslexia (1); glaucoma (1); glioma (1); hepatocellular carcinoma (1); metastatic disease (1); multiple sclerosis (1); Obesity (1); prostate carcinoma (1); Sepsis (1); soft tissue sarcoma (1); temporal lobe epilepsy (1).